EEPD1 (endonuclease/exonuclease/phosphatase family domain containing 1)
Synonyms: KIAA1706; HSPC107
Tractability: Antibody: its Gene Ontology location is reachable by antibodies, with high confidence. PROTAC: ubiquitination databases record sites on it; its protein half-life has been measured.
Gene: Protein-coding gene on chromosome 7 (36,153,075 to 36,301,557, forward strand). Ensembl gene ENSG00000122547.
Subcellular location (Human Protein Atlas): Nuclear speckles; Vesicles
Pathways (Reactome):
Signal Transduction: NR1H3 & NR1H2 regulate gene expression linked to cholesterol transport and efflux
Gene Ontology:
Molecular function: protein binding; catalytic activity; DNA binding
Biological process: positive regulation of cholesterol efflux; DNA repair
Cellular component: plasma membrane
Genetic constraint (gnomAD): Loss-of-function variants: 15 observed, 41.2 expected, observed/expected ratio (o/e) 0.36, 90% interval 0.24 to 0.56. The upper end of that interval is the gene's LOEUF score, 0.56, which puts it in group 2 of 6, group 1 being the genes least tolerant of losing a copy. Missense variants: 600 observed, 684.19 expected, observed/expected ratio (o/e) 0.88, 90% interval 0.82 to 0.94. Synonymous variants: 278 observed, 286.95 expected, observed/expected ratio (o/e) 0.97, 90% interval 0.88 to 1.07.
Homologues: Orthologues: chimpanzee EEPD1 (99% identical), macaque EEPD1 (98% identical), dog EEPD1 (94% identical), pig EEPD1 (94% identical), rabbit EEPD1 (92% identical), guinea pig EEPD1 (91% identical), rat Eepd1 (91% identical), mouse Eepd1 (91% identical), tropical clawed frog eepd1 (66% identical), zebrafish eepd1 (62% identical).